CXCL9 (C-X-C motif chemokine ligand 9)
Diseases named in the same sentence as CXCL9 in open-access papers (continued):
Sharing a sentence is not in itself a finding about the gene and the disease.
infection (continued). "Although we focused here on the role of IFN-γ in stimulating CD14+ monocytes/macrophages to secrete CXCL9 and CXCL10, other factors and cell types may be involved in the actual infection." (PMID 20828409, 2010). "However, by 12 hours after infection, the expression of Ccl2, Cxcl1, Cxcl9, and Cxcl10 in the dLN of WT CHIKV–infected WT mice, but not MARCO–/– mice, was significantly increased in comparison with mock-infected mice." (PMID 38194268, 2024). "Interestingly only Mayotte 2008 induced an increased secretion of IFN-β, CXCL9, CXCL10, and CCL5, and only CXCL11 was increased for both RVFV strains infection." (PMID 37306630, 2023). "Similarly, the consistent overlapping expression of the CXCR3 ligands, Cxcl9, Cxcl10 and Cxcl11 may also be unsurprising as there will be distinct stages of the immune response where CXCR3+ T cells are required to fight infection/disease." (PMID 37934811, 2023). "The expression of CXCL3, CXCL5, and CXCL9 during A. baumannii infection has not previously been quantified, and the role that these effectors play in the outcome of infection is unknown." (PMID 36054235, 2022). "MIG (Monokine induced by gamma interferon), also known as CXCL9, is a member of the CXC subfamily of inflammatory chemokines produced by dendritic cells, B lymphocytes and macrophages, which stimulates the recruitment of T lymphocytes to the sites of infection and/or injury by the CXCR3 receptor." (PMID 35720304, 2022). "Moreover, we found CXCL9 more expressed in CP rather than in BMV through the first week of infection." (PMID 35027063, 2022). "The CXCL9, CXCL10, CXCL11/CXCR3 axis and TNFSF13B play a role in both these recruitment and activation processes, responsible for attracting Th1 cells, cytotoxic lymphocytes and natural killer cells to the site of the infection, and related to B-cell activation, respectively." (PMID 34276658, 2021). "A positive correlation between MIG/CXCL9, IP-10/CXCL10, I-TAC/CXCL11 and MIP-3β/CCL19 and mononuclear cell infiltrates was also observed in previous studies on TBE patients, confirming their potential involvement in lymphocyte extravasation to the site of infection during TBE." (PMID 34277474, 2021). "CXCL9 was not assessed by these studies and, together with IL-10, might represent a potential biomarker to detect asymptomatic infections." (PMID 33407502, 2021). "CXCL9 chemokine gene expression, known to promote migration of effector T cells to infected tissues and protective immune response against T. cruzi, was found to be significantly lower in the hearts of STING-KO mice at day 13 after infection, as was IFN-γ and perforin gene expression." (PMID 35095849, 2021). "Our results demonstrated that vaccination with pcHrp1 or pcHrp1+pcIL-34 could significantly trigger the expression of IL-8, CCL2, CXCL9, CXCL10, and CCL20, indicating that the chemokines were involved in the recruitment of neutrophils, monocytes, Th1 cells, and Th17 cells to the infection sites." (PMID 32231137, 2020). "Notably, the decrease in mDC accumulation, IFN‐γ production, iMOs recruitment, CXCL9 expression, and NK cell migration was independent of viral pathogenicity, as infection with attenuated ECTV failed to restore these processes." (PMID 32657004, 2020). "However, while the NOS2/Arg1 expression ratio remained constantly elevated in DCs isolated from H99γ infected mice at all time points, the CXCL9/FIZZ1 expression ratio peaks at day 7 post-inoculation and declines by day 14, further indicating the infection is being controlled." (PMID 31273203, 2019). "Although specific CD8+ T cells infected expressed higher levels of CXCR3 on cell surface, CD8+ T-cells from the immunized group had a higher migration index compared to specific CD8+ T cells generated only by infection, after the ex vivo stimulation with CXCL9 and CXCL10, but not with CXCL11." (PMID 31356587, 2019).
infection (continued). "However, this seems to be independent on CXCL9, as we found an unaltered CXCL9 secretion by the lack of IL-22 during infection." (PMID 27650379, 2016). "However, infection of mice with mouse-adapted RAVV induces increased IFN-γ, IL-5, IL-12, CCL2, and CXCL9 relative to infection with non-lethal RAVV." (PMID 26426036, 2015). "The infection of DC with LASV or MOPV did not lead to synthesis of the CCL2, 3, 4, 5, 7, 13, and 17 mRNAs (data not shown), whereas an increase in the levels of the mRNAs encoding CXCL9, 10, and 11 was observed in MOPV-infected DC, but not in LASV-infected DC." (PMID 24421914, 2014). "When stimulated through the Fas pathway, HSV-2 infected macrophages do not only undergo apoptosis but may also up-regulate the production of TNF-α, CXCL9 and CXCL10 - chemo-attractants for activated T cells and NK cells necessary to eradicate local infection and inflammation." (PMID 23922974, 2013). "CXCL9 and CXCL10 play an important role in regulating NK cell and T lymphocyte influx to the site of infection and for control of vaginal HSV infection; therefore, modulated production of specific chemokines may be imperative for future vaccine adjuvant candidates." (PMID 23062757, 2012). "CXCL9 and CXCL10 are each induced to relatively high levels within the lungs following spore challenge suggesting that antimicrobial activity may act early in infection against the spore form of the organism." (PMID 21124994, 2010). "However, there was an increase over time in circulating IFN-γ and MIG (CXCL9, a monokine induced by IFN-γ), both members of the type II interferon signaling pathway, which peaked between days 3 and 9 post-infection, and returned to basal levels by day 28 post-infection." (PMID 29215081, 2017). "Therefore, levels of CXCR3 (receptor for CXCL9 and CXCL10), CXCR5 (receptor for CXCL13), CCR5 (receptor for CCL3 and CCL5), and CCR7 (receptor for CCL19) were analyzed on CD45hiCD11bloCD19+ B cells which infiltrated the brain at 7, 14, 30, and 60 days post infection." (PMID 27207308, 2016). "When we inhibited NF-κB and TLR3 separately we did not see an increase in CXCL9 and CXCL10 even following infection with our Hsc70-binding viruses." (PMID 38860860, 2024). "Confirmatory Western blots performed on RRV- and Ro1845VP4-G446R-infected cell culture supernatants revealed increased levels of cytokines CXCL9 and CXCL10 while Ro1845 and RRVVP4-R446G infection did not." (PMID 38860860, 2024). "In contrast, levels of MCP-1/CCL2, NGAL, sTNFRSF1A, CXCL9, MMP-9, lactoferrin, and IL-1α did not significantly change in patients between critical disease in the ICU and upon infection recovery post-ICU." (PMID 33232303, 2021). "Moreover, we observed a positive correlation among CXCL9, IFN-γ, and perforin gene expression in the heart of infected animals, suggesting that CXCL9-mediated recruitment of IFN-γ and perforin-expressing cells may have had a positive impact on parasite control at day 13 after infection." (PMID 35095849, 2021). "We observed that intraperitoneal infection with WSN led to robust upregulation of MIG, also called CXCL9, which, unlike MCP1 and KC, remained at a high level in the pancreas and ovaries 4 days after infection." (PMID 32765481, 2020). "It has been shown that lack of CXCL9 and CXCL10 significantly alters the ability of the host to control genital HSV-2 infection through the mobilization of effector cells to sites of infection." (PMID 23922974, 2013). "Accordingly, IEC isolated from IFNγ−/− neonatal mice did not significantly upregulate the expression of CXCL9 and CXCL10 during the infection whereas other chemokines such as CCL3, CCL4 and CCL5 were still upregulated." (PMID 24367259, 2013). "Finally, there was a group of cytokines and chemokines: TNF, IFNγ, CCL5, CXCL9, CXCL10 and CXCL13, which were early after infection elevated in the vaccinated but not detectable in the naive animals, suggesting an adaptive immune response as the trigger." (PMID 39472590, 2024).
infection (continued). "We found that the majority of CD11b+ LyChi Ly6G- CD64+ inflammatory monocytes present in the ear of VACV-infected mice at 5 days post-infection were CCR5+, the receptor for CCL4, rather than CCR2+, or positive for the receptors for CXCL13 (CXCR5) or CXCL9 and CXCL10 (CXCR3)." (PMID 31603920, 2019). "At this stage of infection, only CCL3 and CXCL9 showed no changes in mRNA expression." (PMID 27688600, 2016). "While IL-17R KO animals predictably had significantly higher amounts of IL-17 in brain abscess homogenates, several other mediators were also elevated between 7 and 14 days after infection, including IL-1α, IL-1β, IL-6, CCL3 and CXCL1 (data not shown), as well as CXCL2 and CXCL9." (PMID 22704602, 2012). "We document a sharp increase in the inflammatory response in terms of Ifng, Tnfa, Il6, Il1b, Il1r1, Cxcl9 and Cxcl10 expression already on day 6 post-infection in WT mice, and of Cd8a on day 7, which were essentially absent in ST2-/- mice on day 5 to 7 after PbA-infection." (PMID 28448579, 2017). "Following CB4 challenge, TLR3KO mice produced similar levels of CCL2 and CXCL9 while levels of CCL3 and CCL4 were slightly reduced but were not significantly different from either WT NOD controls or MyD88KO mice suggesting that these chemokines are not critical for survival following infection." (PMID 19122812, 2009).
cancer (349 papers, 2010 to 2026). A tumor composed of atypical neoplastic, often pleomorphic cells that invade other tissues. "Meta-analysis has shown that high CXCL9 levels are associated with a good response to ICI in several cancers." (PMID 39080202, 2024). "In another study, CXCL9+ TAMs were described as TAMs associated with favorable prognosis in several cancers." (PMID 39507421, 2024). "Among the most recurring ligands, we found several instances that are either invariably associated to lower survival, e.g., CXCL5, CXCL1, GAL, and RPS19, or have opposite associations depending on the cancer type, e.g., CXCL9." (PMID 38723607, 2024). "JAK1 is a critical molecule linking IFNγ receptor activation to activation of all IFNγ-sensitive genes and loss of JAK1 downregulates class II, class I, and CXCL9/10 in cancer cells." (PMID 37565053, 2023). "As visualized in heatmaps, JMJD8 was negatively associated with several chemokines (CXCL9, 10, 11, 12, and 13), many receptors, and immunostimulators in pan-cancer." (PMID 35898493, 2022). "The infiltrations of M1 macrophages, M2 macrophages, and cancer-associated fibroblasts were also higher in CRCs with high CXCL9 expression than in those with low CXCL9 expression." (PMID 36362062, 2022). "All the 14 IFN-γ–associated genes we examined, with the exception of CXCL9, were found to be significantly elevated in cancer cells within TEXhi tumors." (PMID 35132960, 2022). "Experimentally, CXCL9-deficient cancer cells have been shown to be more tumorigenic than cancer cells transduced with CXCL9." (PMID 34206510, 2021). "Because T-DXd, especially DXd has been reported to cause cell cycle-specific DNA damage in HER2-positive cancer cells, it possibly up-regulates the expression of CXCL9/10/11 through the induction of cell cycle-specific DNA damage in HER2-positive GC cells." (PMID 34413454, 2021). "Among them, chemokines CXCL9/10/11 have been proposed as critical because their expression is linked to disease-free survival in cancer patients." (PMID 28986561, 2017). "STAT2 depletion in USP5-deficient cancer cells significantly reduced upregulated CXCL9 and CXCL10 mRNA, as well as CD86 and HLA-DR protein of cocultured THP1-MΦ; these reductions were rescued by restoring WT-STAT2 but not the Y690A mutant in USP5-depleted cells." (PMID 41321309, 2025). "In the context of aging other than cancer cells, research has identified that the most significant factor influencing the inflammatory aging clock (iAge)was the chemokine CXCL9, which has been implicated in the process of cardiac aging, unfavorable cardiac remodeling, and impaired vascular function." (PMID 38590525, 2024). "In light of research has predominantly indicated that CXCL9 is linked to the response to ICI in advanced cancer patients, the observed increase in CXCL9 expression in older individuals, as a response marker for emerging immune-oncology treatments in this population." (PMID 38590525, 2024). "Notably, in 2019, genes such as CD69 and CXCL9 were identified; both are closely linked to immune responses and cancer prognosis, suggesting new directions for research." (PMID 38919494, 2024). "Indeed, CXCL9 is a potential biomarker of immune infiltration associated with favorable prognosis in many cancers and has been reported to be one of the most predictive." (PMID 37492391, 2023). "In addition, IFN-γ produced by T helper 1 (Th1) cells makes macrophages directly cytotoxic to cancer cells, and causes them to secrete angiostatic chemokine ligand 9 (CXCL9) and CXCL10 to inhibit angiogenesis." (PMID 37503572, 2023). "IL-6 and chemokine CXCL-9 are important for the growth and development of tumors, but it is unclear whether baseline cytokine and chemokine levels are associated with overall cancer survival and the development of irAEs." (PMID 34805229, 2021).
cancer (continued). "In addition to the M1 versus M2 phenotyping, an alternative classification method using the relative expression levels of CXCL9 and SPP1 has been introduced to assess macrophage polarity, showing that the CXCL9:SPP1 ratio is associated with prognosis in cancer patients." (PMID 39601163, 2024). "In addition, compared with untreated tumors, tumors treated with SGT-53 showed increased mRNA expression of chemokines including Cxcl9, Cxcl10, and Cxcl12, which are associated with increased infiltration of activated T cells in various human cancers via the chemokine receptors CXCR3 and CXCR4." (PMID 36359830, 2022). "Fibroblast-derived CXCL9/10 also promotes lung metastasis by stimulating the growth of CXCR3+ cancer cells." (PMID 40447617, 2025). "The chemotaxis of Tregs to the TME driven by the CCL17/CCL22-CCR4, CCL1-CCR8, CCL28-CCR10, and CXCL9/10/11-CXCR3 axis has also been a widely studied concept among cancer biologists." (PMID 40852716, 2025). "SFV/IFNγ inhibited cancer-associated pathways (angiogenesis, glycolysis and extracellular matrix (ECM) remodelling) and enhanced cytotoxic lymphocyte (CTL) chemoattractants (CXCL9 and CXCL10)." (PMID 40547518, 2025). "Pan-cancer analysis revealed that CD58 was associated with key immune regulatory factors, including PD-L1, chemokines (CCL5, CXCL9, CXCL10)." (PMID 41438981, 2025). "Follow-up experiments using a baseline serum with a CXCL9 pathway inhibitor also reduced cell viability and growth, highlighting the relevance of CXCL9 in the context of exercise effects on cancer cells." (PMID 40362215, 2025). "To assess their function in cancer, we used Pf4creCx3cr1DTR mice, which predominantly deplete CD206hi IMs, including those that express Cxcl13 (for B cell chemotaxis), Cxcl9 and Cxcl10 (for NK and T cell recruitment), as well as Ccl6, Ccl8, Ccl9, and Ccl2418." (PMID 40630529, 2025). "In a phase I trial of intravenous Helixor® M in advanced cancer patients, treatment resulted in increased levels of CXCL9 and CXCL10, chemokines that mediate the recruitment of cytotoxic T and NK cells to solid tumors." (PMID 40864825, 2025). "Early myeloid architecture dictates cancer fate: dense CXCL9+/CXCL10+ clusters with T-cell enrichment accompany regression, whereas sparse infiltration predicts progression." (PMID 41279770, 2025). "Immunohistochemistry results indicated significantly elevated GALP, CACNA1C, COL16A1, PENK, C4BPA, PSMA2, and CXCL9 expression in cancer tissues." (PMID 38481252, 2024). "Accordingly, CXCL9 strongly correlated with CD8+ T cell abundance in tumors, and high CXCL9 expression predicted better survival in ovarian and other cancer patients when compared to low CXCL9 expression." (PMID 38098230, 2024). "Immunohistochemistry results indicated significant upregulation of GALP, CACNA1C, COL16A1, PENK, C4BPA, PSMA2, and CXCL9 in cancer tissues." (PMID 38481252, 2024). "For instance, CXCL9/10/11 can autonomously bind to their CXCR3a protein, thereby directly promoting the growth and metastatic properties of cancer cells." (PMID 38275602, 2024). "High expression of CCR7, IL2RG, CXCL9 and MAPK10 was associated with elevated drug sensitivity of cancer cells, while high expression of FLT3 was associated with diminished drug sensitivity of cancer cells to one drug (INK-128)." (PMID 38438469, 2024). "Mechanistically, the production of IFN-ɣ by CD16+ NK cells triggered the secretion of CXCL9/10 from cancer cells." (PMID 38167224, 2024). "High expression of CXCL9 and CXCL10 has been strongly associated with improved survival and a substantial increase in the number of intratumoral CD8+ T cells in cancer patients treated with ICIs." (PMID 38434763, 2024). "Our findings highlight the link between C5aR, macrophages, and CXCL9 production in cancer immunotherapy." (PMID 38098230, 2024).